PTMAP2 (prothymosin alpha pseudogene 2)
Gene: Processed pseudogene on chromosome 5 (118,973,796 to 118,974,122, forward strand). Ensembl gene ENSG00000197744.
Diseases named in the same sentence as PTMAP2 in open-access papers:
PTMAP2 is named in the same sentence as 1 disease in open-access papers, as found by Europe PMC text mining. Sharing a sentence is not in itself a finding about the gene and the disease.
PTMAP2 shares sentences with these, for which no sentence is quoted: lung adenocarcinoma (1 paper).